ADORA1 (adenosine A1 receptor)
Diseases named in the same sentence as ADORA1 in open-access papers (continued):
Sharing a sentence is not in itself a finding about the gene and the disease.
tumor (31 papers, 2010 to 2025). "In the context of cancer, THE ADENOSINE A1 RECEPTOR’s signalling mechanisms contribute to the suppression of tumour growth and metastasis." (PMID 40417221, 2025). "Adenosine leads to increased migration of pDCs into the tumor through the adenosine A1 receptor (ADORA1), thus inducing Tregs and consecutively suppressing cytotoxic CD8+ T cells." (PMID 38927922, 2024). "PRODH has been involved in NSCLC metastasis as shown, both in vitro and in vivo, and ADORA1, which is highly expressed in EGFR-mutant NSCLC biopsies, has been associated involved in tumor-immune evasion in NSCLC xenograft models." (PMID 36551790, 2022). "We analyzed the association between ADORA1 and tumor immune cell infiltration, and the relationship between ADORA1 and immune-related modulators using Tumor Immunoassay Resource (TIMER) and TISIDB tools, respectively." (PMID 34093805, 2021). "Unlike adenosine receptor A2AR, A2BR, and A3, one study showed adenosine receptor A1 (ADORA1) signaling axis suppresses tumor PD-L1-mediated immune evasion." (PMID 32775303, 2020). "Downregulation and inhibition of adenosine receptor A1 (ADORA1) significantly induces tumor PD-L1 expression by promoting ATF3 transcriptional activity." (PMID 32775303, 2020). "Extracellular adenosine functions as a ligand that binds to adenosine receptors, such as the ADORA2A, promoting tumor growth by recruitment of MDSCs and ADORA1 that signals downstream of cAMP/PKA/CREB/ATF3/PD-L1." (PMID 32516941, 2020). "In addition, it activates downstream extracellular adenosine (eADO) binding to adenosine A1 receptor (ADORA1) to enhance pDCs recruitment into the tumor." (PMID 40297580, 2025). "Thus, the role of Adora1 (adenosine A1 receptor) in response to hypoxia or other adenosine environmental triggers depends on the tumor type and organ of origin." (PMID 41346607, 2025). "Adenosine A1 receptors (ADORA1) play a role in promoting tumor growth in cancer." (PMID 38361933, 2024). "Moreover, inhibiting ADORA1 expression enhances immune evasion of tumor through modulating ATF3-PD-L1 axis, which is the critical biomarker for ICB response in NSCLC." (PMID 37083272, 2023). "Regarding the various functions of the adenosine A1 receptor in certain diseases, it has been proposed that this receptor may act as a potent regulator of normal and tumor cell growth by having both pro and anti-apoptotic effects." (PMID 37168725, 2023). "ADORA1 Inhibition promotes tumor immune evasion by regulating the ATF3-PD-L1 Axis." (PMID 36291758, 2022). "However, the specific mechanisms by which ADORA1 regulates tumor progression and immune cell infiltration in PTC are unclear." (PMID 34093805, 2021). "Besides, ADORA1 expression was significantly correlated with tumor-infiltrating cells and immune biomarkers in PTC." (PMID 34093805, 2021). "Consequently, the functions of ADORA1 and related genes were primarily involved in tumor immunomodulation and cancer-related pathways, suggesting that ADORA1 may mediate the tumorigenesis and progression of PTC." (PMID 34093805, 2021). "Noteworthy, tumor cells can express adenosine A1 receptor (ADORA1) and ADORA3 receptors coupled to Gαi proteins, fostering tumor cell proliferation and migration." (PMID 29720980, 2018). "The tumor cells from the endometrium, esophagus, thyroid, and kidneys show dominant expressions of receptors like RXRA (Retinoid X Receptor Alpha), RXRB, PPARG, and ADORA1 (Adenosine A1 Receptor), underscoring their diverse physiological roles." (PMID 39766077, 2024). "The result showed that five genes (PRKCA, ADORA1, PPARGC1A, KL, GNG7) could be identified as potentially prognostic factors, and they have also been suggested as tumor suppressor genes." (PMID 31661791, 2019). "Higher ADORA1, lower ATF3, and lower PD-L1 expression levels were noted in tumor tissues from non-responders among anti-PD-1 antibody (nivolumab)-treated NSCLC patients." (PMID 32516941, 2020).
tumor (continued). "The proteins ADIPOR1, ADORA1 and CD46 did not demonstrate differences in expression between tumours from alive and dead patients." (PMID 20553615, 2010).
cancer (21 papers, 2015 to 2025). A tumor composed of atypical neoplastic, often pleomorphic cells that invade other tissues. "The top 25 enriched KEGG pathways associated with ADORA1 miRNA targets are primarily related to cell proliferation, apoptosis, and cancer." (PMID 40667070, 2025). "In conclusion, 13 cancer-induced somatic mutations located at the 7-transmembrane domain of the adenosine A1 receptor were retrieved from TCGA and characterized in a robust yeast system." (PMID 35744872, 2022). "Interestingly, on the promoters of factors like IL6 and ADORA1, which are upregulated in cancers and are associated with poor prognosis, histone acetylation was found to be significantly repressed upon luteolin treatment." (PMID 26517526, 2015). "Prior research has suggested that the adenosine A1 receptor (ADORA1) facilitates the proliferation of tumors in cancer." (PMID 40376586, 2025). "Adenosine A1 receptor (AA1R) has been shown to have an inhibitory effect on cell growth in several cancers; however, its function in esophageal cancer is still unclear." (PMID 37168725, 2023). "According to previous studies, the adenosine A1 receptor (AA1R) plays a critical role in the pathogenesis of different cancers, such as breast, colorectal, melanoma, and renal cancers." (PMID 37168725, 2023). "Genes often found to be epigenetically silenced or with low expression levels in ovarian or other cancers (Adora1, Bmp3, Ccl6, Ephx2, Lefty2, Pf4, Socs2) were downregulated by MOSE-LTICv in the OFB." (PMID 38264656, 2023). "Given the limited information on ADORA1 in cancer pathophysiology, the observed anticancer effects can be attributed to the inhibition of the other two targets (TRIM24 and CDK2)." (PMID 37894709, 2023). "ADORA1, an adenosine A1 receptor, is a G-protein-coupled receptor family member that binds adenosine to activate cancer downstream signaling cascades." (PMID 36290882, 2022). "Adenosine A1 Receptor (ADORA1) is an adenosine receptor particularly relevant to the immunomodulatory process of malignant tumors, with four family members (ADORA1, ADORA2a, ADORA2b and ADORA3) playing regulatory roles in vitro." (PMID 34093805, 2021). "STK11, a kinase involved in the regulation of ADORA1, was aberrantly expressed in various tumors and played a role in promoting cancer cell adhesion and angiogenesis." (PMID 34093805, 2021). "The functions of ADORA1 co-expressed genes were mainly enriched in immune response, immune response-regulation signaling pathway, regulation of leukocyte activation and cancer-related pathways." (PMID 34093805, 2021). "The AdoRA1, for example, had an antiproliferative effect and promoted the differentiation of cancer stem cells, thereby inducing an increased sensitivity of these cells to chemotherapeutic drugs." (PMID 33194619, 2020). "The resulting antitumor activity may, in turn, be derived from the inhibition of important molecular targets involved in cancer pathogenesis, including ADORA1, CDK2, and TRIM24." (PMID 37894709, 2023). "Overexpression of the adenosine A1 receptor (A1AR) has been detected in various cancer cell lines." (PMID 35744872, 2022). "It has been previously documented that ADORA1 may mediate the immune microenvironment to influence cancer progression and immune regulation 18-20." (PMID 34093805, 2021). "ADORA1 and the top 4 significant genes, including MYBPH, FAM178B, CHI3L1 and METTL7B were selected as the hub genes for genetic variation, interrelationship, cancer pathway and drug susceptibility analysis." (PMID 34093805, 2021). "These evidences all suggest that ADORA1 may mediate the immune microenvironment to influence cancer progression and the regulation of immunity." (PMID 34093805, 2021). "Moreover, ADORA1 exerted a modulatory effect on cancer cell proliferation and differentiation by manipulating the MAPK signaling pathway." (PMID 34093805, 2021).
cancer (continued). "Moreover, a growing number of reports indicated that ADORA1 could influence the development, progression and metastasis of various kinds of cancers by mediating immune processes." (PMID 34093805, 2021). "Upregulated GPCRs that have been proposed as therapeutic targets in cancer included the adenosine receptors ADORA1 and ADORA3, and important GPCRs for autocrine growth factors in cancer, such as bombesin receptor NMBR, and neurotensin receptor NTSR145,46." (PMID 36220861, 2022). "The results showed that these five genes, especially ADORA1, could activate EMT, Hormone ER, PI3K/AKT, RAS/MAPK, TSC/mTOR pathways, and inhibit RTK, Hormone AR, DNA Damage Response, Cell Cycle, Apoptosis pathways to exert regulatory effects in cancer process." (PMID 34093805, 2021). "Besides, our data showed that ADORA1 could activate EMT, Hormone ER, PI3K/AKT, RAS/MAPK, TSC/mTOR pathways and inhibit RTK, Hormone AR, DNA Damage Response, Cell Cycle, Apoptosis pathways to exert regulatory effects on the cancer process." (PMID 34093805, 2021).
psychiatric disorder (4 papers, 2011 to 2022). A disorder characterized by behavioral and/or psychological abnormalities, often accompanied by physical symptoms. "Our earlier association studies in Polish patients with GTS have revealed a relationship between some SNPs of BTBD9, ADORA1 and ADORA2A genes and co-morbid psychiatric disorders." (PMID 32194619, 2020).
cardiac diseases (2 papers, 2011 to 2023). "Taken together, these studies confirm the importance of ADORA1 in the pathobiology of heart diseases, but do not explain how the differential up-regulation of this receptor in adjacent adipose tissues may affect myocardial or vascular function." (PMID 21603615, 2011).
metabolic disease (2 papers, 2021 to 2022). A congenital disorder (due to inherited enzyme abnormality) or acquired (due to failure of a metabolically important organ) disorder resulting from an abnormal metabolic process. "It is also well established that abnormal signaling via the adenosine A1 receptor pathway contributes to some metabolic diseases." (PMID 36014488, 2022). "This is a relevant regulation given that an abnormal adenosine A1 receptor signaling contributes to some metabolic diseases." (PMID 34557353, 2021).
cardiovascular diseases (1 paper, 2011). "Despite this similarity, two genes involved in cardiovascular diseases, ADORA1 and PTGDS, were differentially up-regulated in EAT." (PMID 21603615, 2011). "Interestingly ADORA1 was the most significant gene differentially expressed between EAT and MAT, but also the gene more highly linked to cardiovascular diseases in IPA." (PMID 21603615, 2011).
liver (1 paper, 2024). "Blockade of ADORA1 using an antagonist or genetic knockout protects against ethanol-induced fatty liver or alpha-naphthyl isothiocyanate-induced intrahepatic cholestatic liver injury." (PMID 39060559, 2024).
ADORA1 also shares sentences with these, for which no sentence is quoted: cardiac arrhythmias (2 papers); heart failure (2); kidney cancer (2); leukemia (2); acute kidney injury (1); acute lung injury (1); Alcohol (1); angiosarcoma (1); bipolar affective disorder (1); breast tumour (1); bronchiolitis (1); Cerebral ischemia (1); childhood asthma (1); chlamydia (1); colorectal adenocarcinoma (1); demyelinating disease (1); dyslipidemia (1); Epstein-Barr virus infection (1); head and neck squamous cell carcinoma (1); Heat Stroke (1); hypertrophic cardiomyopathy (1); insomnia (1); iron deficiency (1); methamphetamine dependence (1); multiple sclerosis (1); neurodegenerative disease (1); neuropathic pain (1); non-small cell lung carcinoma (1); pancreatic adenocarcinoma (1); panic disorder (1).
A further 6 diseases each share a sentence with ADORA1 in 1 paper.